MYCN (MYCN proto-oncogene, bHLH transcription factor)
Diseases named in the same sentence as MYCN in open-access papers (continued):
Sharing a sentence is not in itself a finding about the gene and the disease.
tumor (continued). "c‐MYC, which has the overall structure and organization of genes and transcripts similar to MYCN, may be responsible for partial response to ceftriaxone of tumor cells expressing the c‐MYC rather than MYCN." (PMID 37975412, 2024). "Notably, enforced expression of MYCN in mouse migrating NCCs leads to the development of NB-like tumors, while its overexpression in SA progenitors is not sufficient for neoplasia." (PMID 38069407, 2023). "Clinical genomic evaluation of the tumor showed no alterations in the MYCN or ALK genes." (PMID 36980535, 2023). "One tumor with PLAGL2 amplification (#A113—excluded from the core DNA methylation cohort due to QC issues, but with a clear signal for ET, PLAGL), harbored additional focal high-level amplifications of the MDM4 oncogene on chromosome 1q32.1 and the MYCN oncogene on chromosome 2p24.3." (PMID 36437415, 2023). "We then stratified the patients in each cohort based on whether or not MYCN is amplified in the tumours and based on their stages." (PMID 36695333, 2023). "We suspect that alterations to ß-oxidation alongside the inhibition of complex I may hamper mitochondrial energy production, thus explaining these augmented anti-tumor effects, suggesting that the combination of MET and KD is an effective adjuvant therapy to CP in MYCN-amplified NB xenografts." (PMID 37623854, 2023). "While MYC is ubiquitously and highly expressed in cells throughout development and in adult tissues, MYCL expression is predominantly restricted to both neonatal and adult lung tissue; in contrast MYCN expression is tumor specific and is not usually expressed in human adult tissues." (PMID 36765949, 2023). "The key molecular steps that support MYCN-driven tumor initiation are not entirely resolved." (PMID 37958555, 2023). "In addition, we note that numerous previous studies have shown that either inhibition of the downstream target genes of MYCN alone or its own regulatory function failed to completely inhibit tumour growth." (PMID 37461251, 2023). "However, the importance of this potential protein as a tumor promotion factor, prognostic biomarker, and therapeutic candidate has not been elucidated in clinical NB with and without MYCN amplification." (PMID 37760452, 2023). "Interestingly, on subgroup analysis of MYCN non-amplified tumor samples, we found that CCL2 expression was higher in advanced stage tumors, while it exhibited decreased expression in MYCN-amplified advanced stage tumors." (PMID 37964011, 2023). "Interestingly, we also compared their expression levels between tumor and normal tissues and found that the expressional changes were complex, especially significantly upregulated genes (CDKN2A, MYCN, PLK1, and TERT) and some downregulated signatures (AXL, ID1, and TLR3)." (PMID 35754848, 2022). "Furthermore, depletion of SLC27A2 reduced tumor proliferation (Ki67 staining, p = 0.004) and increased tumor apoptosis (cleaved Caspase-3 staining, p < 0.0001) without altering MYCN expression (p = 0.4)." (PMID 35764645, 2022). "Thus, tumor cells promote MYCN expression and N-MYC protein levels via multiple mechanisms." (PMID 35883689, 2022). "Thus, MYCN does not seem to contribute to ATR inhibitor sensitivity in ARMS to the same extend as it does in other tumor entities." (PMID 35879366, 2022). "Moreover, JQ1 and CDK inhibitor dinaciclib showed synergistic effect on the induction of cytotoxicity in MYCN amplified NB cells but the combination of AZD5153 and dinaciclib reduced the tumor size in mice models in vivo through increasing the tumor necrosis and lymphocyte infiltration." (PMID 36187481, 2022).
tumor (continued). "Furthermore, GPC2 and CD276 expression levels were independent of the tumor’s MYCN amplification status." (PMID 35852863, 2022). "Therefore, the combination of the tumor genomic pattern (GG-P2s and BP ≥ 7) with age at diagnosis and LDH will be a promising predictor for MYCN-non-amplified high-risk NBs in patient subsets, in accordance with previous findings from the INRG project." (PMID 35053166, 2021). "It is therefore conceivable that our EPN lines, enriched in stem-like cells, express a high MYCN/MYC ratio, that is switched by differentiation, similarly to what may occur in EPN specimens, where SCs represent only a restricted population of the tumor burden." (PMID 33668642, 2021). "Noteworthy, with respect to NB the tumor-suppressive effects of GLI activation might be restricted to the large subset of patients not harboring MYCN gene amplifications." (PMID 33921042, 2021). "Interestingly, we found that patients with ITH analysed by pangenomic techniques had a significantly better survival rate that those with non-heterogeneous tumours, especially in cases without MYCN amplification." (PMID 34680323, 2021). "Moreover, FAIM2 transcription was enriched in primary tumor cells without MYCN amplification as compared to those with MYCN amplification, thus supporting previous findings." (PMID 34503120, 2021). "Interestingly, we also saw higher expression of immune checkpoints in MYCN-NA tumors with increased CD8+ T-cell infiltrates, which is supported by previous findings that signaling from T-cells can upregulate immune checkpoint expression by tumor cells." (PMID 35464627, 2021). "Unfortunately, negativity of MYCN amplification in cells from metastatic bone marrow could not prove MYCN nonamplification of tumor because of tumors' heterogeneity." (PMID 32896084, 2020). "In the data sets analyzed in this work, only 9 stage 4S NB patients presented MYCN amplified tumor; however, we could not analyze either the E2F3 expression or its relation with survival of this group of patients." (PMID 32429447, 2020). "MYCN-amplified NB tumor specimens express higher levels of CHK1 mRNA than non-MYCN-amplified NB cells, suggesting that the sensitivity of such NB cells to CHK1 inhibition may be related to high levels of MYCN-induced RS." (PMID 31362335, 2019). "Of note, miR-323a-5p overexpression impaired tumor growth in the MYCN-amplified cell line, but not in SK-N-AS, suggesting that higher doses of miR-323a-5p or being functional for longer periods of time may be needed to achieve a therapeutic effect." (PMID 30770954, 2019). "In addition to loss of large regions on chr1p, 3p, and 11q and a broad gain of chr17q, VCF2CNA found frequent focal amplifications of MYCN in NBL tumors and several potential cancer-related CNAs, including high-level amplifications of CDK4 (1 tumor), and ALK (2 tumors)." (PMID 31316100, 2019). "It is possible that the tissue sections used for the IHC (although from the same paraffin block used for FISH) did not include the tumor component that harbors the amplification, or, even though the MYCN gene was amplified, the tumor cells, indeed, did not express the protein." (PMID 31365300, 2019). "Furthermore, we compared the presence of SYK protein in MYCN-amplified and non-MYCN-amplified tumor tissue and did not observe differences between the two groups." (PMID 30744170, 2019). "Two tumors of the Dbh-MYCN model in this set are derived from the same mouse and are designated “multiple primaries” as they occur in the left and right adrenal glands, which would not be a typical metastatic spread of an adrenal derived tumor." (PMID 29492199, 2018).
tumor (continued). "Moreover, the higher malignant potential of I-cells does not depend on the status of amplification of MYCN, which is usually an indicator of aggressive behavior of the tumor." (PMID 30116755, 2018). "Accordingly each tumor was determined to have either MYCN protein overexpression [MYCN protein (+)] or MYCN protein negative/weak expression [MYCN protein (−)/(+/−)] and either MYC protein overexpression [MYC protein (+)] or MYC protein negative/weak expression [MYC protein (−)/(+/−)]." (PMID 29464082, 2018). "IL-6 and IL-6R have been shown to promote tumor growth, and we previously identified the IL6R gene as one of the inflammation-related genes in a 14-gene prognostic signature in children with high-risk tumors lacking MYCN amplification." (PMID 29207662, 2017). "However, many HR-NB tumours harbour a normal MYCN locus, termed MYCN-non-amplified (MN) NB, suggesting the existence of other genetic markers." (PMID 28246384, 2017). "To determine if MYC family proteins could cooperate with MCPyV IMR90 cells, we treated cells stably expressing ST, GFP, or p53DD + hTERT (PH) and MCPyV tumor-derived early-region (PHE) with inducible expression of MYC, MYCN or MYCL with dox for 48 hours and immunoblotted for HK2, MCT1 and LDHA." (PMID 27880818, 2016). "This signature could discriminate between MYCN-amplified and non-amplified tumours even when corrected for MYCN effects (F-test, p-value = 1.8E-50." (PMID 27531891, 2016). "For 12/71 (17%) tumor samples, no RB1 mutations or MYCN amplification could be found by WES (WES negatives)." (PMID 27126562, 2016). "Thus, in a technique relying on extracted bulk DNA such as SNP array, the high number of MYCN copies in single cells is equaled out by a high number of non-amplified tumor cells, resulting in a copy number status below the MYCN amplification threshold." (PMID 27560999, 2016). "Finally, tumor-derived endothelial microvessels were coated by host derived pericytes that never showed MYCN amplification." (PMID 26925422, 2016). "We chose the SH-SY5Y cell line as an example of a MYCN non-amplified tumor with relatively slow growth, and the NGP cell line as an example of a MYCN amplified tumor with relatively fast growth, although not as fast as the MAT-B-III model we studied previously." (PMID 27861510, 2016). "Importantly, TPT-treated senescent tumor cells act growth-inhibitory in a dose-dependent manner on non-senescent tumor cells and MYCN expression is significantly reduced in vitro and in vivo." (PMID 26657295, 2016). "Importantly, in some tumours, MYCN protein levels can also be very high without gene amplification or high mRNA levels, implicating other factors that might stabilize MYCN at the protein level; as expected, high MYCN protein is closely associated with very poor prognosis." (PMID 25475372, 2015). "Furthermore, even in non-MYCN-amplified tumours, a MYCN-amplified transcriptional signature is observed, and levels of c-Myc can also be elevated, together suggesting that Myc signalling is an underlying driver of NB tumorigenesis." (PMID 25786414, 2015). "In fact, we found MYCN amplification in tumor sample of a unilateral patient RB30 (data not shown)." (PMID 25928201, 2015). "Of note, we analyzed 41 representative blood samples from the patients in our cohort and observed that all these patients have the same SNP status in their blood as in their tumor (data not shown), indicating that CASP8 SNP D302H is a germline risk factor for NB patients with MYCN amplification." (PMID 25502557, 2014). "One could speculate that MYCN is an even better antigen for immunotherapy because it is almost exclusively expressed by tumor, but not normal, cells." (PMID 26029658, 2014). "Type 2A tumours have near-diploid or near-tetraploid karyotypes dominated by structural rearrangements, most prominently 17q gain and 11q deletions, still with absence of MYCN amplification." (PMID 23555645, 2013).
tumor (continued). "However, tumours having numerical aberrations in combination with amplification of MYCN or other structural chromosome changes generally do not share this favourable course of disease." (PMID 23555645, 2013). "In these studies, the results of southern blotting and FISH analysis were prospectively compared and a MYCN copy number of ≥ 10 was determined to be the optimal cutoff by FISH, as the vast majority of amplified tumors have very large numbers of double minutes in each tumor cell." (PMID 23320395, 2013). "The student's t-test showed that high expression of LMO3 was significantly associated with ≥1 year of age (p = 0.036), low expression of TrkA (p = 0.003) and MYCN amplification (p = 0.04), but not with the tumor stage (p = 0.17), tumor origin (p = 0.083) and Shimada classification (p = 0.082)." (PMID 21573214, 2011). "In one tumour, the ΔMYCN transcript could not be identified, but this is probably because ΔMYCN is low expressed in general and in this tumour MYCN was not amplified." (PMID 19615087, 2009). "However, survival analyses in a large study using 75 MYCN-amplified tumours indicate that neither amplified DDX1 nor NAG have an additional adverse effect on the prognosis of the patients." (PMID 19615087, 2009). "In addition, significantly higher expression values were also found for GATA-2 in tumours without MYCN-amplification and stage 4S tumours (vs stage 4)." (PMID 19707195, 2009). "Similarly, analysis of FOG-2, GATA-2 and GATA-3 expression by real-time RT-PCR disclosed only lower FOG-2 levels in MYCN-amplified vs MYCN-nonamplified tumours at a significant level." (PMID 19707195, 2009). "We have now performed chromosomal CGH of NB samples obtained from centres of the SFCE in a single laboratory, in order to determine if pangenomic genotyping could be useful for the management of MYCN non-amplified tumours in a clinical setting." (PMID 17579628, 2007). "Moreover, the genes that were differentially expressed in subgroups of advanced stage patients without MYCN amplification accurately separated MYCN amplified tumours from low stage tumours without MYCN amplification." (PMID 17531100, 2007). "We combined gene expression data from two studies in a meta-analysis in order to investigate differences in gene expression of advanced stage (3 or 4) tumours without MYCN amplification that show contrasting outcomes (alive or dead) at five years after initial diagnosis." (PMID 17531100, 2007). "Additionally, patients younger than 18 months who are classified as having stage MS disease and whose tumor does not have MYCN amplification with all favorable features (histology, diploidy, or segmental chromosomal aberrations) are also classified as low risk." (PMID 40507292, 2025). "Therefore, the approaches discussed in Section 2.2 and Section 3.5, focusing on targeting MYCN and ALK, may be used not only to target tumor growth, but to alleviate immune evasion mechanisms, and their effect could be further potentiated by combining them with immunotherapeutic approaches." (PMID 40507292, 2025). "Although treatment with 792 and 1154 decreased MYCN expression, we hypothesize that the lack of a larger effect on cell viability or tumor growth is likely due to the ability of cancer to proliferate via other oncogenic pathways, indicating a need for combination therapy." (PMID 35454859, 2022). "To check whether the effect of NRTI on tumor recurrence following chemotherapy is a general phenomenon or is limited to the MMTV-HER2/Neu–17-DMAG model, we used another spontaneous cancer model with a well-characterized response to chemotherapy, the Th-MYCN mouse model." (PMID 36449545, 2022). "Previously this could only have been identified from tumor tissue in enucleated eyes; however, the work herein demonstrates the ability to detect this from the aqueous humor (alongside methylation signatures of multiple other genes including SYK, MYCN, and others)." (PMID 36130950, 2022).
tumor (continued). "Moreover, the block of MYCN by the anti-MYCN BGA002 is able to reactivate and restore the effectiveness of natural killer immune cells against NB, reverting the role of MYCN as a driver of a tumor immunosuppressive environment which impacts survival in several MYCN-positive tumors." (PMID 36139583, 2022). "However, MYCN non-amplified tumours often present high levels of expression of MYC (c-MYC), which might explain why PKM2 and hexokinase II levels were similar in vesicles from the two groups of patients." (PMID 34847775, 2021). "However, we observed a significant difference (p-value < 0.01) in the number of SCAs between tumour types related MYCN status when we distributed data into quartiles, with ITH non-MNA tumours having more SCAs (average 13.3) than non-ITH non-MNA ones (average 8.8)." (PMID 34680323, 2021). "Indeed, there were a few differences between patient tumor, PDOX, and cell line, such as NTRK1 mutation detected in the autopsy sample of SJ-DIPGX37, but not the associated PDOX or cell line, or MYCN amplification present in SJ-DMGX40 PDOX, but not in the matched patient tumor." (PMID 34215733, 2021). "The effect of MYCN-MAX on tumor growth coupled with the observation that GD2 is able to enhance angiogenesis, thereby increasing the supply of blood borne nutrients needed by proliferating tumor cells, supports the hypothesis that they act synergistically to enhance/maintain cell growth." (PMID 32726962, 2020). "Except for one case in which no viable residual tumor was available in the post-therapy resection specimen to perform MYCN IHC, all the remaining 15 cases (93.75%) in which MKI could not be assigned had concordant results (FISH positive/IHC positive, n = 7; FISH negative/IHC negative, n = 8)." (PMID 31365300, 2019). "In addition, we expanded this analysis for two primary patient-derived tumor cell lines (one MYCN amplified and one MYCN non-amplified organoid grown in stem cell medium) for which we tested viability for drug combinations after 5 days of treatment and observed even stronger synergism." (PMID 30451831, 2018). "MYCN and ALK copy number assessment from plasma at diagnosis could also identify patients with possible subclonal amplifications, and this analysis should accompany tumor biopsy analyses to test its clinical predictive power for possible future use in treatment stratification." (PMID 29156716, 2017). "This suggests that, in general, Cre-mediated excision should be sufficient to achieve a tumor penetrance of 100%, but also that MYCN expression may be variable and that a threshold sufficient for tumor development may not be reached in tumor-free LSL-MYCN;hGFAP-Cre mice." (PMID 27769070, 2016). "Also for tumor T7, from a non-familial unilateral patient, both high-level amplification of MYCN and RB1 inactivation was observed (20 nucleotides frameshift insertion in exon 1; NM_000321:c.25ins20:pT9fs), although RB1 inactivation was missed by WES because of low exon 1 coverage." (PMID 27126562, 2016). "However, the observation may provide one explanation for the selective expression in MYCNlow tumor cells, since expression of integrins without appropriate ligands may promote apoptosis in MYCN amplified cells." (PMID 25973900, 2015). "In contrast, mutations and CN alterations affecting cell cycle regulators, such as MYCN, CDK4 and CDKN2A/B, except for MDM2, were particularly enriched in the A1/A2 clusters compared with the E1/E2 clusters (P=0.016), suggesting that these genes may have driver roles in A1/A2 tumours." (PMID 26138366, 2015).